DRAXIN (dorsal inhibitory axon guidance protein)
Description:
Chemorepulsive axon guidance protein required for the development of spinal cord and forebrain commissures. Acts as a chemorepulsive guidance protein for commissural axons during development. Able to inhibit or repel neurite outgrowth from dorsal spinal cord. Inhibits the stabilization of cytosolic beta-catenin (CTNNB1) via its interaction with LRP6, thereby acting as an antagonist of Wnt signaling pathway.
Synonyms: C1orf187; FLJ34999; Neucrin; AGPA3119; UNQ3119
Tractability: Antibody: UniProt places it where antibodies can reach, with high confidence; UniProt predicts a signal peptide or a membrane-spanning region; its Gene Ontology location is reachable by antibodies, with medium confidence. PROTAC: its protein half-life has been measured.
Gene: Protein-coding gene on chromosome 1 (11,690,958 to 11,725,857, forward strand). Ensembl gene ENSG00000162490.
Subcellular location: Secreted
Gene Ontology:
Molecular function: molecular adaptor activity; protein binding
Biological process: axon guidance; commissural neuron differentiation in spinal cord; dorsal spinal cord development; forebrain development; negative regulation of canonical Wnt signaling pathway; anterior commissure morphogenesis; negative regulation of neuron projection development; Wnt signaling pathway
Cellular component: extracellular region
Genetic constraint (gnomAD): Loss-of-function variants: 27 observed, 34.41 expected, observed/expected ratio (o/e) 0.78, 90% interval 0.58 to 1.08. The upper end of that interval is the gene's LOEUF score, 1.08, which puts it in group 4 of 6, group 1 being the genes least tolerant of losing a copy. Missense variants: 371 observed, 476.75 expected, observed/expected ratio (o/e) 0.78, 90% interval 0.71 to 0.85. Synonymous variants: 178 observed, 203.18 expected, observed/expected ratio (o/e) 0.88, 90% interval 0.77 to 0.99.
Homologues: Orthologues: chimpanzee DRAXIN (99% identical), macaque DRAXIN (97% identical), pig DRAXIN (84% identical), rabbit DRAXIN (79% identical), dog DRAXIN (78% identical), guinea pig DRAXIN (77% identical), mouse Draxin (77% identical), rat Draxin (77% identical), tropical clawed frog draxin (39% identical), zebrafish draxina (37% identical), zebrafish draxinb (33% identical).
Diseases named in the same sentence as DRAXIN in open-access papers:
DRAXIN is named in the same sentence as 10 diseases in open-access papers, as found by Europe PMC text mining. Sharing a sentence is not in itself a finding about the gene and the disease. The quoted sentences say what the papers report.
glioma (2 papers, 2022 to 2025). A benign or malignant brain and spinal cord tumor that arises from glial cells (astrocytes, oligodendrocytes, ependymal cells). "Our results showed that high expression of the oncogene DRAXIN in tumor tissue and cells could be used as an independent risk factor for poor prognosis in glioma patients and was strongly associated with clinical risk features." (PMID 36040678, 2022). "Both experiments indicated that knockdown of DRAXIN significantly inhibited the proliferation ability of glioma cells." (PMID 36040678, 2022). "Collectively, for the first time, DRAXIN was found to be highly expressed in gliomas as an oncogene leading to shorter survival and poor prognosis of patients." (PMID 36040678, 2022). "The rigor of the analysis for aberrant expression of DRAXIN in glioma was improved by validation using GEPIA, CGGA database, IVY-GAP database and basic experimental RT-qPCR and IHC." (PMID 36040678, 2022). "The aim of this study was to reveal the function of DRAXIN in glioma from multiple perspectives and its impact on patient treatment and prognosis." (PMID 36040678, 2022). "Firstly, we demonstrated that DRAXIN expression is much higher in glioma tissues and cell lines compared to normal samples." (PMID 36040678, 2022). "In the primary glioma, the expression of DRAXIN in IDH wild-type was higher than that of the mutant (p < 0.001)." (PMID 36040678, 2022). "Overall, the experiments confirmed the high expression of DRAXIN in glioma through multidimensional evidence." (PMID 36040678, 2022). "At the tissue level, IHC results demonstrated that protein levels of DRAXIN increased in glioma samples in comparison with normal brain tissue and was the highest in Grade IV glioma." (PMID 36040678, 2022). "Second, the experiments further verified that mRNA levels of DRAXIN were increased in gliomas using laboratory brain tissue samples, and were also significantly higher in glioma cell lines, especially in A172 cells, compared to HA cell." (PMID 36040678, 2022). "The present study also confirmed that DRAXIN could promote the invasion of glioma cells, as other oncogenes have been reported." (PMID 36040678, 2022). "In order to achieve the purpose of revealing the specific mechanism of DRAXIN in glioma, GSEA analysis was firstly applied to reveal the cancer-related cell signaling pathways that DRAXIN might involve in." (PMID 36040678, 2022). "Moreover, the role of DRAXIN in promoting glioma proliferation and invasion has also been demonstrated." (PMID 36040678, 2022). "It is believed that this study will provide DRAXIN as an effective biological target for the prognosis of glioma and may provide new research directions for the drug treatment of glioma." (PMID 36040678, 2022). "Finally, in vitro experiments demonstrated that knockdown of DRAXIN significantly inhibited proliferation and invasion of glioma cell." (PMID 36040678, 2022). "DRAXIN may not only benefit to explore the pathogenesis of gliomas, but also serve as a novel biological target for the treatment of glioma." (PMID 36040678, 2022). "On the other hand, ETNPPL, a gene inversely associated with DRAXIN, is also negatively associated with the grade of glioma as its expression is not detected in glioblastomas." (PMID 36040678, 2022). "Then, a series of bioinformatics analyses were performed to mine data from information of glioma samples extracted from several reputable databases to reveal the key role of DRAXIN in glioma development and progression, with the confirmation of basic experiments." (PMID 36040678, 2022). "Furthermore, to explain the role of DRAXIN itself in glioma, individual top ten most related genes were obtained after screening the p value and correlation coefficient value of co-expressed genes." (PMID 36040678, 2022). "In summary, the expression of DRAXIN was significantly related to the malignant features of glioma." (PMID 36040678, 2022).
glioma (continued). "Enrichment in focal adhesion and Toll-like receptor signaling pathway also remind us that DRAXIN may partake in migration and tumor immunity of glioma." (PMID 36040678, 2022). "Overall, DRAXIN does promote cell proliferation capacity and invasive ability in glioma." (PMID 36040678, 2022). "Besides the correlation with shorter OS, DRAXIN expression was found positively correlated with glioma WHO Grade, 1p19q non-co-deficiency, GBM and recurrent GBM." (PMID 36040678, 2022). "After Wilcox and Kruskal tests, it was concluded that the increased expression of DRAXIN was positively correlated with higher WHO grade and recurrent and secondary glioma (p < 0.001)." (PMID 36040678, 2022). "The high expression levels of DRAXIN have been observed in small-cell lung carcinoma (SCLC), as well as in glioma tumor tissues and cell lines; DRAXIN has been proposed to function as an oncogene, as its knockdown significantly inhibits the proliferation and invasion of glioma cells." (PMID 40508156, 2025). "An increasing number of evidences have shown that the carcinogenic effect of DRAXIN plays an important role in the malignant process of tumors, but the mechanism of its involvement in glioma has not yet been revealed." (PMID 36040678, 2022). "Compared to gliomas with 1p19q co-deletion status, the expression level of DRAXIN was higher in that with non-co-deletion state (p < 0.001)." (PMID 36040678, 2022). "In addition, DRAXIN may be involved in the cell cycle and VEGF pathway to affect the progression of gliomas." (PMID 36040678, 2022). "Nevertheless, the molecular mechanism of DRAXIN in glioma has not been reported." (PMID 36040678, 2022). "However, the expression of DRAXIN in glioma has not been reported, so the present study is the first of its kind to clarify the relationship between DRAXIN and characteristics of glioma." (PMID 36040678, 2022).
autism spectrum disorder (1 paper, 2023). A spectrum of developmental disorders that includes autism, and Asperger syndrome. "Finally, DRAXIN plays a role in neural development and has been implicated in autism spectrum disorder and obsessive-compulsive disorder." (PMID 36631443, 2023).
lung adenosquamous carcinoma (1 paper, 2022). "When this idea is extended to tumor field, DRAXIN is reported to be a key factor in the progress of lung adenosquamous carcinoma via the regulation of cell proliferation and apoptosis." (PMID 36040678, 2022).
tumor (5 papers, 2022 to 2025). "QRT-PCR showed that the expression of the DRAXIN, ITPRID2, and MAP3K1 were significantly upregulated while MOXD1 was downregulated in tumor samples." (PMID 36045691, 2022).
DRAXIN also shares sentences with these, for which no sentence is quoted: cancer (1 paper); glioblastoma (1); lung carcinoma (1); metabolic disorders (1); obsessive-compulsive disorder (1); small cell lung carcinoma (1).